KRAS (KRas proto-oncogene, GTPase)
Diseases named in the same sentence as KRAS in open-access papers (continued):
Sharing a sentence is not in itself a finding about the gene and the disease.
breast cancer (continued). "Furthermore, recent studies have shown the synergistic effect of ZOL and trametinib (MEK inhibitor) to inhibit growth and colony formation of MDA-MB-231 breast cancer cells, but also potentiate the antitumor activity in KRAS mutant tumors both in vitro and in vivo." (PMID 35625883, 2022). "More importantly, the activation of endogenous mutant KRAS and expression of exogenous KRAS specifically in luminal epithelial cells in a continuous and differentiation stage-independent manner induces preneoplastic lesions that evolve into basal-like and claudin-low mammary cancers." (PMID 34145248, 2021). "After establishing the Flp recombinase-based mammary cancer model expressing mutant KRAS, we embarked on a study to determine whether it was technically possible that Flp can serve a dual purpose for the subsequent activation or deletion of genes in established mammary tumors." (PMID 34675248, 2021). "When BRAF V600E and non-synonymous changes in KRAS or NRAS were considered, methylation of the 5′UTR of C7orf49 and of the probe cg00172872 in the intergenic region on 12q21.33 remained significantly associated with trametinib in pancancer and breast cancer (5.24 × 10–13 ≤ pFDR ≤ 0.0023)." (PMID 33676569, 2021). "Thus, targeting BCL2L1-HRAS by APG-1252 may offer potential therapeutic strategies for treatment of KRAS mutant breast cancer." (PMID 32101536, 2020). "However, the role of miR-143 plays in inhibition of KRAS signaling pathways in breast cancer remains unclear." (PMID 32370060, 2020). "Interestingly, despite the absence of prevalent mutations of KRAS in breast cancer patients, silencing of KRAS significantly inhibited cell viability in most TNBC lines compared to non-TNBC lines, consistent with pathway activation reported in TNBC." (PMID 30777101, 2019). "Thus, expression of YB-1 in cytoplasmic and nuclear fractions was tested after irradiation in tumor cells from different origins, i.e., in the KRAS(G13D)-mutated breast cancer cell line MDA-MB-231, in the KRAS(Q61H)-mutated NSCLC cell line H460, and in the KRAS(G12V)-mutated NSCLC cell line A549." (PMID 30126195, 2018). "Therefore, the effects of KRasG12V signaling observed in the context of the mammary cell line may be interpreted as a general response, since KRas mutants play a negligible role in the biology of breast cancer." (PMID 27894102, 2016). "Furthermore, we confirmed that miR-200c could inhibit KRAS expression and suppress the proliferation and clone formation of breast cancer cells in vitro." (PMID 26392416, 2015). "To analyze the biological consequences of the miR-200c-driven repression of KRAS in breast cancer cells, we investigated whether increasing or decreasing the expression of miR-200c would have an impact on cell proliferation and clone formation in MBA-MD-231 and 4T1 cells." (PMID 26392416, 2015). "However, association of KRAS mutations with resistance to anti-EGFR therapies has not been established in breast cancers." (PMID 23601074, 2013). "EGFR mutations and KRAS mutations either do not occur or are exceptional in breast cancer." (PMID 21966417, 2011).
breast cancer (continued). "Based on the TCGA database, we identified 119 TNBC patients among 1059 primary breast cancer cases and assessed the prognostic significance of MYC, KRAS, and CD274 (PD‐L1) mRNA expression." (PMID 41020311, 2025). "Breast cancer treatment involves targeting key genes involved in cell proliferation, differentiation, and apoptosis, such as PIK3CA, CCND1, HER2, STAT3, WNT1, and KRAS." (PMID 40284420, 2025). "KRAS protein was overexpressed in MCF7 TIS cells, despite its typically marginal expression in breast cancer cells and tumors." (PMID 40312750, 2025). "For instance, our previous investigation suggested LINC00960 to promote breast cancer via the hsa-miR-34a-5p, hsa-miR-16-5p, BMI1, KRAS, and AKT3 network." (PMID 39995981, 2025). "In breast cancer, the SOST gene was found to interact with signal transducer and activator of transcription 3 (STAT3) and enhance TGF-β/KRAS (Kirsten rat sarcoma virus) signaling, leading to increased tumor growth and bone metastasis." (PMID 38247829, 2024). "Independently of intracellular lipid levels, oncogenic drivers, including KRAS and PI3K, promote de novo lipogenesis in breast cancer (BC) and other cancer types converging on mTORC1 activation." (PMID 37045819, 2023). "For breast cancer patients, known oncogenes and tumor suppressor genes such as ESR1, KRAS, PIK3CA, PIK3R1, FAT1, and MED12 were consistently identified in both ctDNA and tumor WES across patients." (PMID 37878600, 2023). "Enrichment analysis revealed that the terms “epithelial-mesenchymal transition” and “KRAS signaling UP” were enriched in the upregulated genes, confirming that the MDA-MB-231 cells represent an aggressive and mesenchymal phenotype of breast cancer cells." (PMID 37762678, 2023). "KRAS and LKB1 comutant NSCLC emulates claudin-low breast cancer, and GFPT2 was reported in different studies to be the key player in boosting the malignancy of this type of malignant lung cancer." (PMID 34923141, 2022). "Previous works showed high expression of HRAS, KRAS, and NRAS in breast cancer compared with benign breast tissue; deletions of HRAS but no other mutations in RAS family members; and rare amplifications." (PMID 36358725, 2022). "KRAS, NRAS and HRAS, referred to as oncogenic RAS, gained our attention from the viral carcinogenesis pathway, breast cancer pathway and renal cell carcinoma pathway." (PMID 35422066, 2022). "We found that TMEM176B expression on breast cancer cells was important for cell proliferation and migration, AKT/mTOR signaling, and the regulation of a number of genes involved in angiogenesis, KRAS signaling, EMT, and estrogen and interferon responses." (PMID 34943938, 2021). "The literature provides data on validated targets, such as KRAS for miR-181c-5p, or SOX2 for miR-625-5p, which are important oncogenes in breast cancer." (PMID 34439180, 2021). "Genes including hTERT, HER2 (ERBB2), HRAS, KRAS and c-MYC confer increased proliferative capacity in breast cancer." (PMID 34988459, 2021). "We also explored the impact of HERV expression in its neighboring breast cancer development genes (BRCA1, CCND1, NBS1/NBN, RAD50, KRAS, PI3K/PIK3CA) and in long non-coding RNA expression (AC060780.1, also known as RP11-242D8.1)." (PMID 33194615, 2020). "However, we did also observe KRAS activation using pathway analysis of RNA-seq data collected from metastatic PDX lung tumors compared to matched primary mammary gland tumors, suggesting that KRAS pathway activation may be an important mechanism for at least some breast cancer patients." (PMID 32463822, 2020).
breast cancer (continued). "Previous studies have demonstrated that KRAS/MAPK and PI3K/AKT signaling pathways play a critical role in breast cancer progression, growth, and survival." (PMID 32370060, 2020). "Phloroglucinol, isolated from the brown alga E. cava, diminished the population of breast cancer cell lines (MCF7, SKBR3 and BT549) in tumors, by inhibiting KRAS and its downstream PI3K/Akt and RAF-1/ERK signaling pathways." (PMID 33007997, 2020). "The feature enriched the term oncogenic signature (C6) “KRAS.600.LUNG.BREAST_UP.V1_UP” that comprised the genes that were up-regulated in epithelial lung and breast cancer cell lines overexpressing an oncogenic form of KRAS gene." (PMID 32346383, 2020). "(c) UAG (100 pM) suppresses cell growth of basal-like and mesenchymal-like TNBC breast cancer cell lines that are WT for BRAF and KRAS (6–9 replicates/group)." (PMID 32667883, 2020). "(B, C) A combined panel of selected breast cancer and near-normal cell lines was reverse-transfected with 10 nM pooled JAK1, JAK2, STAT3 or KRAS siRNAs and cell viability determined after 6 days." (PMID 30777101, 2019). "Breast cancer cells treated with etomoxir to inhibit CPT1A resulted in cell death, while in vivo, mutant KRAS lung tumours were dependent on ACSL3-dependent FAO for tumour initiation and progression." (PMID 30092766, 2018). "For MCF-7 breast cancer cells, data showed a significant decrease in the mRNA levels of BCL-2, KRAS and NRAS oncogenes and some of the YWHA family." (PMID 29444163, 2018). "Next, ASSIGN was used to estimate the activation of each GFRN member (AKT, BAD, EGFR, HER2, IGF1R, KRAS (G12V), and RAF1) in 1119 breast cancer patient samples from TCGA and 55 samples from the ICBP panel of breast cancer cell lines." (PMID 28446242, 2017). "To date, let-7 has been reported to target HRAS and KRAS, miR-200c and miR-30c target KRAS, miR-148b targets NRAS, miR-7 targets RAF1, miR-206 targets RASA1 and miR-21 targets SPRED1 in breast cancer cells." (PMID 27705918, 2017). "Interestingly, we also observed that the breast cancer cell line MDA MB 231 that expresses oncogenic KRAS (which is not a commonly acquired mutation in this type of cancer) shows higher levels of expression of S100A10 compared to the breast cancer cell line MCF7 that express WT KRAS." (PMID 27351226, 2016). "In the future, we will examine additional genes such as MYC, KRAS, and ERBB2 in breast cancer and other cancers." (PMID 27846853, 2016). "The oncogenetic tree model was built on CNV of ErbB2, AKT2, KRAS, PIK3CA, PTEN, and CCND1 genes in 963 cases of tumors with sequencing and CNA data of human breast cancer from TCGA." (PMID 27190992, 2016). "Combination therapy has been proven to be effective in multiple cancer types, such as PI3K and MEK inhibition in KRAS or EGFR driven cancers and mTOR and aromatase inhibition in breast cancer." (PMID 26509262, 2015). "Furthermore, expansion of the number of BRCA1 mutation carriers by including other family members in addition to the index cases in the study by Hollestelle and colleagues did also not improve significance, nor did the KRAS variant appear to modify breast cancer risk for BRCA1 mutation carriers." (PMID 22436609, 2012). "For the first time, we have identified somatic mutations in genes related to the AKT/MAPK signaling pathways, such as EGFR, PIK3CA, KRAS, HRAS and NRAS, in brain metastases of breast cancer and other types of cancer." (PMID 20604919, 2010).
breast cancer (continued). "None of the hallmark cancer pathways, except for KRAS, were significantly enriched to high GALNT1 expression breast cancer by GSEA." (PMID 37444599, 2023). "NF1 loss-of-function mutations, RTKs mutations such as ERBB2 activating mutations, as well as alterations in other MAPK pathway genes (EGFR, KRAS, BRAF, and MAP2K1) were found to be enriched in endocrine-resistant advanced ER+ breast cancer compared to early-stage ER+ breast cancer." (PMID 38003387, 2023). "While KRAS and FGFR2 alterations are infrequent in breast cancer, these alterations may be extremely significant in the prognosis and treatment of their disease." (PMID 37805590, 2023). "Interestingly, when we assayed two additional breast cancer cell lines, MDA MB-231 and T-47D, we found that KRAS transcript levels were decreased." (PMID 36477459, 2022). "The proportion of alterations of KRAS and BRAF differed significantly among breast cancer subtypes (Fisher exact test two-sided p = 1.566 × 10−12 and p = 1.355 × 10−11, respectively), with both genes more frequently altered, mainly due to amplification, in basal-like tumors." (PMID 36358725, 2022). "We selected breast cancer SCP2 cells that are prone to bone metastasis to explore the molecular mechanisms and found that SOST promoted the proliferation of breast cancer cells by enhancing the STAT3/TGF-β/KRAS signaling." (PMID 36581888, 2022). "The AURORA study found KRAS and NF1 to be among the significantly mutated driver genes in breast cancer but not enriched in metastatic lesions." (PMID 36358725, 2022). "From analyses of the same three patient breast cancer datasets, we find HIF1A transcripts and its transcriptional targets, CAIX and VEGFA, and G3BP1 (but not NRF2) are all significantly higher in breast cancers that exhibit gain of function or amplified KRAS." (PMID 34294889, 2022). "Webgestalt ORA of the TCGA DEG illuminated positive enrichment in MLL3 mutants for “genes upregulated in ER+ breast cancer samples” and “KRAS‐dependency signature genes,” and negative enrichment for “genes downregulated in ER+ breast cancer samples”." (PMID 34581028, 2021). "For example, KRAS and PI3K have been found to cooperate in the production of de novo lipid biogenesis and RAS oncogenesis is exaggerated when the cyclin-dependent kinase inhibitor (p21WAF1/CIP1) is depleted in breast cancer." (PMID 33801965, 2021). "Due to the occurrence of KRAS-induced tumors in other organs, in particular, the skin but also the salivary gland and ovary (not shown), a further examination of mammary cancer progression and metastasis was not conducted in this model." (PMID 31937792, 2020). "While KRAS is not considered a major driver of breast cancer, recent work implicates this factor as an important player for some subtypes." (PMID 32463822, 2020). "In contrast, a separate group found 20% of KRAS- variant T > G breast cancer cases in a Czech population to be HER2 negative, and 3% of KRAS-variant cases to be HER2 positive." (PMID 30897768, 2019). "The active mutants of HRAS, KRAS, and NRAS were found in a subset of breast cancers." (PMID 30111373, 2018). "To confirm that BH4-dependent interactions between KRAS and BCL-XL account for its effect on RAS signalling, we used a BRET-based RAS activity sensor in epithelial human breast cancer MCF-7 cells stably overexpressing equivalent levels of wild type or BH4-deleted BCL-XL." (PMID 29066722, 2017). "This analysis identified 30/229 known cancer genes (T200 targeted platform) and 11/40 TCGA breast cancer genes that were differentially expressed relative to the normal breast cells, including KRAS, GATA3, CCND1, CDH1, GNAS, and several others." (PMID 28794488, 2017).
breast cancer (continued). "KRAS signaling and MYC targets v1 gene sets were de-emphasized in the BRCA + OV + UCEC model, pointing to a less prominent role of these pathways in determining breast cancer disease progression." (PMID 28916782, 2017). "In addition, miR-133a targeting of EGFR, miR-200c and miR-30c targeting of KRAS, miR-148b targeting of NRAS, miR-7 targeting of RAF1, miR-206 targeting of RASA1 and miR-21 targeting of SPRED1 have been reported in breast cancer cells." (PMID 27462780, 2016). "Indeed, evidence exists for a high cost–benefit ratio for identifying patients with KRAS and BRAF wild-type metastatic colorectal cancer suitable for treatment with cetuximab and those with HER2-positive breast carcinomas who will respond to trastuzumab." (PMID 26942417, 2016). "Previous studies on KRAS expression have shown a discrepancy between the primary tumour and corresponding lymph node metastases, whereas the expression of other biomarkers, e.g. ER and HER-2 in breast cancer have been demonstrated to be highly concordant." (PMID 23819542, 2013). "A negative correlation between miR-30c expression and KRAS protein level was observed in two breast cancer cell lines." (PMID 22701724, 2012). "One of these miRNAs, miR-30c, potentially contributes to breast malignancy formation through release of KRAS suppression suggesting that this miRNA, and likely other miRNAs also targeting KRAS/MAPK signaling, may function as tumor suppressors in breast cancer." (PMID 22701724, 2012). "In lung and breast cancer cell line panels, the RAS pathway signature score correlates with pMEK and pERK expression, and predicts resistance to AKT inhibition and sensitivity to MEK inhibition within both KRAS mutant and KRAS wild-type groups." (PMID 20591134, 2010). "In this context, synthetic peptide inhibitors with submicromolar binding affinity to mutant KRAS have been used to inhibit the PPI between the intracellular RAS and its downstream signaling partner rapidly accelerated fibrosarcoma (RAF), suggesting a potential therapeutic strategy for breast cancer." (PMID 40236954, 2025). "However, our on-chip indicates that KRAS activation and EGF exposure are required to promote conversion to a stem-like phenotype and induce the most robust tumor response when used to seed a mouse breast cancer model." (PMID 40487641, 2025). "In addition, we lacked a comparison between in-house testing and CGP for KRAS/G12C, RET mutations, and NTRK rearrangements in NSCLC; and for PIK3CA mutations in breast cancer." (PMID 36832270, 2023). "NR2F1-high primary breast cancer amplified multiple pathways related to metastasis: Epithelial Mesenchymal Transition (EMT), angiogenesis, as well as enhanced cancer stem cell-related pathways, including KRAS signaling, Notch signaling, Hedgehog signaling, and Wnt/β-catenin signaling." (PMID 35740627, 2022). "The main distinction between the MMTV-tTA and EF1-tTA-based mammary cancer models is that the Eef1a1 locus drives a constitutive expression of the tTA and oncogenic KRAS in neoplastic cells independent of their differentiation state, which allows them to assume diverse developmental fates." (PMID 34145248, 2021). "In contrast to other models where pregnancy greatly accelerates the development of mammary cancer, the latency of mammary tumor formation in the mutant KRAS-expressing females was not significantly affected by parity (165 days, N = 10, in virgin versus 136 days, N = 9, in parous mice; P > 0.2)." (PMID 34675248, 2021).